IL6 (interleukin 6)
Diseases named in the same sentence as IL6 in open-access papers (continued):
Sharing a sentence is not in itself a finding about the gene and the disease.
COVID-19 (continued). "However, it is worth noting that most of the currently tested immunomodulatory agents (especially anti-IL-6, anti-IL-1β, and anti-TNFα) have been put forward despite gaps in our understanding of the immune response behind COVID-19 ARDS, especially within the pulmonary compartment." (PMID 33138839, 2020). "Tocilizumab can effectively block the IL-6 signal transduction pathway and could conceptually become an effective drug for patients with severe COVID-19 since significant morbidity and mortality in the late phase of disease is attributed to severe cytokine release storm (CRS))." (PMID 33292763, 2020). "Therefore, some scholars pointed out that peripheral blood IL-6 could be applied as a key factor to independently predict the progression of COVID-19." (PMID 33042873, 2020). "Therefore, anti-IL-6 therapy could potentially have detrimental consequences if given too early in patients with COVID-19, before the full effect of the antivirals has been established." (PMID 33033405, 2020). "In addition, CAM with its pleiotropic effects on cytokines including IL-6 and indirect antiviral effects might be worth a try for treating COVID-19." (PMID 33014130, 2020). "Moreover, as a mediator of SASP, IL-6 is the main functional marker of cell aging, and the increase in IL-6 content may correspond to the age-dependent increase in mortality of COVID-19 patients." (PMID 33269102, 2020). "Emerging evidence implicates IL6 as a central mediator of toxicity in cytokine release syndrome (CRS); therefore, these findings suggest that a rapid and severe deterioration during SARS-CoV-2 infection into COVID-19 is associated with CRS/cytokine storm syndrome." (PMID 32668803, 2020). "Higher vitamin D levels correlate with lower interleukin 6 levels, which are a major target for controlling cytokine storm in COVID-19.41,42 To the extent that it prevents infection, decreases viral replication, or accelerates viral clearance, vitamin D treatment might reduce spread." (PMID 32880651, 2020). "Furthermore, a significantly close relationship between IL-6 levels in critical COVID-19 patients with fatal outcome (64.0 pg/ml, IQR 25.6–111.9) and RNAemia was found, in particular, the 83.3% of patients with IL-6 > 100 pg/ml had positive levels of RNAemia, r 0.902." (PMID 32527304, 2020). "Interestingly, high levels of IL-6 were detected in newborns from COVID-19 mothers." (PMID 32574261, 2020). "We hypothesize that TNF-α and IL-6 may contribute to the occurrence of CSS in COVID-19." (PMID 33584719, 2020). "Importantly, elevation of IL-6 levels in severe COVID-19 patients was later than that of CCL5." (PMID 32766256, 2020). "This indicates that COVID-19 patients who have previously experienced poverty, and/or institutional racism, especially at a young age, might react to COVID-19 with an overproduction of cytokines, including IL-6, accelerating the cytokine storm and worsening disease prognosis." (PMID 33134238, 2020). "The seventh edition of the Chinese Clinical Guidance for COVID-19 Pneumonia Diagnosis and Treatment published by China National Health Commission on 4 March 2020 included tocilizumab as an option for patients with severe COVID-19, extensive lung lesions, and elevated IL-6 levels." (PMID 32423024, 2020). "Current evidence suggests that even though COVID-19 significantly impairs tissue function, much of the tissue injury is mediated by the resultant IL-6-driven cytokine storm that exacerbates pulmonary injury and may further damage other peripheral organs as has been reported for SARS." (PMID 32867708, 2020). "However, interleukin (IL)-6—a pleiotropic cytokine released by T cells, endothelial cells, fibroblasts, macrophages, and monocytes in acute and chronic inflammatory phases—appears to play a central role in the pathogenesis of COVID-19-related CRS." (PMID 33110739, 2020). "In addition, Tocilizumab (anti-IL-6 treatment) showed clinical improvement in COVID-19 patients." (PMID 33193349, 2020).
COVID-19 (continued). "In addition, elevated ferritin and IL-6 levels observed in 150 confirmed COVID-19 cases suggested that virus-induced hyperinflammation might be one leading cause of fatal outcome." (PMID 32574261, 2020). "Therefore, upregulation of IL6 and NFkB genes may be contribute to the inflammatory symptoms observed in severe COVID-19 patients." (PMID 32511341, 2020). "In COVID-19 patients, innate immune cells, including dendritic cells and macrophages, were activated upon sensing of coronaviruses via toll-like receptors, which induced the expression of pro-inflammatory cytokines (e.g., IL-1, IL-6, TNF-a) through engagement with NF-κB signaling." (PMID 33195318, 2020). "In addition, it has been suggested that cytokines involved in COVID-19 severe pathogenesis, such as IL-1 and IL-6, may be potential therapeutic targets." (PMID 32766251, 2020). "Amongst the participants hospitalized with COVID-19, we report that a higher prevalence of detectable SARS-CoV-2 plasma viral load is associated with worse respiratory disease severity, lower absolute lymphocyte counts, and increased markers of inflammation, including C-reactive protein and IL-6." (PMID 33127906, 2020). "Thus, we suggest that monoclonal antibodies targeting GM-CSF or interleukin 6 may be effective in blocking inflammatory storms and, therefore, be a promising treatment for severe COVID-19 patients." (PMID 34676125, 2020). "The fatal outcome of COVID-19 may be primarily due to a single cytokine (i.e., IL-6)." (PMID 32766256, 2020). "However, other results such as the lack of a linear correlation between the Delta a-cv lactate and IL-6 levels require caution with the interpretation of the study results, in particular about the role of immunosuppressive drugs in the treatment of the COVID-19." (PMID 33014462, 2020). "IL-6 may play an important role in the generation of headache attributed to COVID-19." (PMID 33391152, 2020). "However, considering the rapid widespread increase in severe cases of COVID-19 worldwide, the availability and the cost of anti-IL-6 treatment might limit its use." (PMID 32817707, 2020). "In this perspective, we present evidence of potential connections between the observed health disparities and COVID-19 progression/severity based on immune regulation and response, particularly from natural killer (NK) cells, monocyte/macrophages, and the cytokine, interleukin-6 (IL-6)." (PMID 33134238, 2020). "Furthermore, some reports suggest that perpetual elevation of IL-6 may even be related to the progression of acute viral infections, including COVID-19, and the inhibition of IL-6′s effects may have beneficial effects on mitigating the disease." (PMID 32485858, 2020). "Indeed, vitamin D supplementation could protect against acute respiratory tract infection and, even more interestingly for COVID-19, has been shown to reduce circulating IL-6 in critically ill patients." (PMID 32867855, 2020). "In an experimental model of ARDS, which is associated with high severity and mortality among COVID-19 patients, the DPP4 inhibitor sitagliptin decreased histological signs of lung injury by hindering the release of pro-inflammatory cytokines IL-1β, TNFα, and IL-6." (PMID 32719619, 2020). "A subgroup of patients with severe COVID-19 may have a cytokine storm syndrome, and treatment of hyperinflammation using existing therapies such as IL-6 inhibitors (tocilizumab and sarilumab), and interleukin 1 receptor antagonists (IL-1RA) (anakinra) may reduce the mortality." (PMID 33352654, 2020). "Furthermore, the putative driving role of IL-6 in SARS-CoV-2 induced inflammation suggests that inhibition of Janus kinases may be an attractive therapy for severe COVID-19 patients." (PMID 32983152, 2020). "Besides He4 together with IL6 might be involved in the onset of smell and/or taste disorders and it might be used as innovative biomarker to monitor clinical evolution of COVID-19 because He4 could indicate a multi-organ involvement." (PMID 33147871, 2020).
COVID-19 (continued). "For COVID-19, dynamic changes in hematologic and immunologic markers, such as progressive decline in eosinophils, lymphocytes, and platelets and dynamic increases in NEUs, IL-6, PCT, D-dimer, and CRP, during hospitalization are indeed strong suggestions for progression of the disease." (PMID 33157938, 2020). "Finally, anti-inflammatory cytokines like anti-interleukin 6 and administration of mesenchymal stromal/stem cells may serve as potential immune modulatory therapies for supportively combating COVID-19." (PMID 32806722, 2020). "Furthermore, in a daily transcriptomic profiling of whole blood from COVID-19 patients, the mRNA expression levels for most of the examined inflammatory genes including IL-6, except the IL-1 family, which are elevated early, reached peaks after respiratory function nadir." (PMID 32766256, 2020). "However, CoVs, such as COVID-19, also present as a hyperactivation of the inflammatory response that results in increased production of inflammatory cytokines such as interleukin (IL)-1β and its downstream molecule IL-6." (PMID 33149733, 2020). "New data have also demonstrated that antibodies targeting IL-6/IL-6R/gp130 such as tocilizumab, siltuximab and clazakizumab could be employed for the therapy of COVID-19, as was also recommended by the National Institute of Health (NIH COVID-19 Treatment Guidelines, 2020)." (PMID 33114676, 2020). "Thus, whether the off-label use of anti-IL-6 signaling agents for COVID-19 could increase secondary infections is indeed a matter of concern." (PMID 33384605, 2020). "A recent review examined whether IL-6 concentrations might affect the outcome of COVID-19." (PMID 33142828, 2020). "Given the activation of BTK and production of IL-6 that we detected in COVID-19 monocytes, we propose that BTK inhibitors target pathological monocyte/macrophage activation and dampen the cytokine storm, which consequently may improve outcomes in these patients." (PMID 32503877, 2020). "Moreover, the positive modulation of IL-6R and IL-6 expression in the adipose tissue of obese individuals may participate in the uncontrolled inflammation observed in COVID-19." (PMID 33322168, 2020). "After analyzing the blood samples of 33 severe and critical type ill COVID-19 patients, Wei Haiming’s team found that after novel coronavirus infection, T cells were overactivated to produce granulocyte-macrophage colony-stimulating factor (GM-CSF) and interleukin-6 (IL-6)." (PMID 32296910, 2020). "In the cluster of cytokine signaling, IL-1 and IL-6 signaling pathways were negatively correlated, while IL-4 and IL-12 signaling pathways were positively correlated, shows that IL-4 and IL-12 have more significant effects on COVID-19 lung tissue than other cytokines." (PMID 33264345, 2020). "In COVID-19 patients, overproduction of cytokines, such as IL-6, might activate coagulation pathways, with a resultant disruption of procoagulant–anticoagulant homeostasis, induction of disseminated intravascular coagulation, and multiorgan dysfunction or failure." (PMID 32765283, 2020). "Thus, if anti-IL-6 therapies are used too early to treat patients with COVID-19, this strategy could potentially inhibit viral clearance and/or leave the patients susceptible to recurrent infection with SARS-CoV-2." (PMID 32704352, 2020). "Thus, some researchers have suggested that the activation of CD26 on T lymphocytes may partially contribute to the high expression of IL-6 in COVID-19 patients." (PMID 33269102, 2020). "Indeed, reduced type I and III IFN abundance in blood transcriptome accompanied by enhanced cytokine (including IL-6) and chemokine levels are speculated to contribute to COVID-19 pathogenesis." (PMID 32595947, 2020). "Importantly, during influenza NAMs suppress IL-6 production, indicating that NAMs may be a critical control point in determining IL-6 levels, and thus may regulate the cytokine storm in COVID-19 patients." (PMID 33101306, 2020).
COVID-19 (continued). "Moreover, elevated IL-6 and IL-10 levels in COVID-19 cases can suppress NK cell activity." (PMID 32973527, 2020). "Finally a systematic review on the role of biomarkers in COVID-19, which looked at 26 different articles, concluded that IL-6 CRP, LDH, D-dimer, troponin, blood urea nitrogen and creatinine were elevated while leukocyte count is decreased in patients with severe SARS-CoV-2 infection." (PMID 32992775, 2020). "Interestingly, patients with severe COVID-19 exhibited higher levels of plasma IL-6 and expressed lower levels of HLA-DRA and HLA-DRB1 in their peripheral blood and BALF monocytes/macrophages than individuals who were negative to SARS-CoV-2 or those with mild disease." (PMID 33036180, 2020). "Higher percentages of granulocyte-macrophage colony-stimulating factor-positive (GM-CSF+) and IL-6+ CD4+ T cells have been observed on patients in intensive care units (ICUs) compared with non-ICU patients with COVID-19, thus indicating that the cytokine storm is associated with disease severity." (PMID 32664543, 2020). "Indeed, patients with COVID-19 have elevated blood levels of multiple inflammatory cytokines and chemokines (IL-1β, IL-6, IL-7, IL-8, IL-9, IL-10, G-CSF, GM-CSF, IFN-γ, IP-10, MCP-1, and MIP-1α), and those requiring admittance to an intensive care unit have even higher levels of many of these." (PMID 32503877, 2020). "Additionally, a significant increase in monocytes producing IL-6 was noted in mild COVID-19 patients (N = 21), and this was increased further in patients with severe disease (N = 12), suggesting that monocytes are key contributors to cytokine storm in COVID-19." (PMID 32556942, 2020). "A study of 74 COVID-19 patients reported that surviving patients had significantly higher H2S levels than non-survivors, and that serum H2S levels negatively correlated with serum IL-6, CRP, and procalcitonin (markers for bacterial infection, sepsis, and tissue injury)." (PMID 33330130, 2020). "Production of IL-6 by monocyte, dendritic cells, and macrophage in patients with severe COVID-19 leads to systematic pro-inflammatory cytokines and CRP production and in the absence of anti-inflammatory cytokines may lead to a high-grade inflammation and cytokine storm." (PMID 32876941, 2020). "Additionally, we chose to focus on the role of IL-6 over other cytokines as (a) IL-6 is consistently shown in the literature to be altered by psychosocial stress or environmental factors, and (b) its importance in COVID-19 severity is highly suggested based on available treatments." (PMID 33134238, 2020). "Interleukin 6 (IL-6), interferon gamma-induced protein 10 (IP-10), tumor necrosis factor (TNF) α and interleukin 1β (IL-1β) implicated as inflammatory factors associated with COVID-19 progression were detected in the alveoli with diffuse immune cell infiltration." (PMID 34676085, 2020). "In our study, we also found that, compared to mild cases, the serum levels of IL-10, TNF-α and IL-6 were significantly higher in the severe cases, indicating that severe cases are prone to form an inflammatory storm, leading to rapid deterioration of COVID-19 eventually." (PMID 33154753, 2020). "Similarly, an elevated level of ferritin and IL-6 in 150 multicenter COVID-19 confirmed cases suggested that virally driven hyper-inflammation might be the reason for mortality." (PMID 33133071, 2020). "In addition, the causal attribution of IL-6 blockade is not straightforward since COVID-19 patients already face an increased risk of developing infectious complications, in particular those with prolonged ICU stays." (PMID 33110739, 2020). "Increased level of HMGB1 can induce proinflammatory cytokine (TNF, IL-1, and IL-6) release, and since chronic inflammatory diseases result in HMGB1 increase, the severity in COVID-19 patients with underlying inflammatory comorbidities could be correlated to HMGB1 levels." (PMID 32948238, 2020).
COVID-19 (continued). "COVID-19 may activate a dysregulated host immune response leading to elevated IL-6 levels." (PMID 32775090, 2020). "An enhanced production of IL-6 is also observed in epithelial cells following infection with A. fumigatus, suggesting that, at least in some patients, the co-infection may contribute to the increased levels of this cytokine in severe COVID-19 patients." (PMID 32599813, 2020). "However, LDH, CRP, and IL-6 values were not significantly different between COVID-19 ARDS patients and patients with non-COVID-19-associated pneumonia (each p > 0.05)." (PMID 33123171, 2020). "Whole blood RNA-profiling indeed showed that critically-ill COVID-19 patients initiate inefficient type I IFNs-responses, have reduced ISGs and persistent (blood-borne) viral load, and show an exacerbated inflammatory response driven by IL6, TNF, and IL1β/IL1RA." (PMID 32719686, 2020). "Additionally, we review current evidence regarding cytokine release syndrome in COVID-19 and the use of IL-6 receptor inhibition as a therapeutic strategy, and examine other reported cases in the literature describing IL-6 antagonist treatment for patients with COVID-19." (PMID 32635353, 2020). "Interestingly, the numbers of total T cells, CD4+ T and CD8+ T cells are negatively correlated to levels of TNF-α, IL-6, and IL-10, respectively, suggesting these cytokines may be involved in the decrease of T cells detected in COVID-19." (PMID 32425950, 2020). "However, inhibition of IL-6 has not yet demonstrated its ability to reduce the death rate in severe COVID-19, although it was associated with seemingly better outcomes of COVID-19 in patients who survived." (PMID 33335532, 2020). "Emerging data suggest that many patients with COVID-19 may die due to an excessive response of their immune system, characterised by the abnormal release of circulating cytokines including IL-1β, IL-6, IL-12, IL-18, TNF-α, TGF-β, GM-CSF, IFN-γ and various chemokines." (PMID 33014130, 2020). "Thus, IL-6 can promote a pro-coagulant and pro-thrombotic vascular pathology, raising the possibility that an abnormally high level of IL-6 may contribute to the vascular phenotype in severe COVID-19." (PMID 32629875, 2020). "In the present study, we investigated the distribution of copy number variations (CNVs) and genetic variants located within the coding sequences of IL6 and IL6R genes, which may be employed as prognostic and drug response (pharmacogenetic) biomarkers for COVID-19 and neuroinflammatory diseases." (PMID 33339153, 2020). "Given the current state of the COVID-19 epidemic and possible efficacy of IL-6/IL-6R inhibition with the use of Tocilizumab, we believed a deeper analysis of the mechanistic/biologic effects of Tocilizumab could further elucidate the effects of the drug on our immune system." (PMID 33469465, 2020). "However, IL-6 neutralization might lead to a variety of immunomodulatory mechanisms potentially contributing to its therapeutic activity in COVID-19 treatment." (PMID 32636755, 2020). "In addition, this study indicated that although COVID-19 patients with severe illness in the first days from symptoms onset exhibited augment of IL-6 and IL-10, at late days from symptoms onset, they showed increased levels of IFN-α and IFN- λ, IL-17, IL-22, eotaxin, IL-13, and a reduction of IL-6." (PMID 33584667, 2020). "In conclusion, the risk factors for COVID-19 patients to develop from moderate to severe condition consists of: complicated common underlying diseases, respiratory frequency, lymphocyte count, blood glucose, albumin, urea, inflammatory factor (CRP, IL-6), and imaging manifestations." (PMID 33042873, 2020). "Finally, CQ inhibits the synthesis of a myriad of pro-inflammatory cytokines such as TNF-α, IL-1, and IL-6, which may have deleterious effects on COVID-19 prognosis." (PMID 32423024, 2020).